MC4R (melanocortin 4 receptor)
Diseases named in the same sentence as MC4R in open-access papers (continued):
Sharing a sentence is not in itself a finding about the gene and the disease.
Obesity (continued). "The results indicate that regular meal frequency attenuates genetic predisposition to increased BMI in terms of both single gene variants (FTO rs1421085 and MC4R rs17782313) and a multiple-locus indicator (a genetic risk score based on eight obesity-susceptibility loci)." (PMID 24040077, 2013). "By the token of “same pathway" evidence, MC4R interactors, whether agonists or antagonists, may be predicted to be linked to obesity." (PMID 23633938, 2013). "Indeed, several pathogenic mutations of the MC4R were identified at a high frequency in severe early-onset obesity in humans." (PMID 23739675, 2013). "In both studies, we genotyped six SNPs that are known to be associated with risk of obesity in European populations: rs17782313 near MC4R; rs2815752 near NEGR1; rs7754561 near ENPP1; rs1805081 in exon 6 of NPC1; rs10938397 near GNPDA2 and rs1421085 in intron 1 of FTO." (PMID 23375129, 2013). "In addition, SH2B1 was associated only with class I/II obesity and MC4R only with class III obesity." (PMID 23950976, 2013). "There was, however, a tendency towards an association between MC4R, obesity and BMI." (PMID 23431394, 2013). "In the fully adjusted model (sex, age, center, diabetes, total energy intake and physical activity, each variant allele (FTO or MC4R) of the additive score increased the odds of obesity by 7% (OR = 1.07; 95%CI: 1.01–1.13) for the continuous aggregate score variable)." (PMID 23284998, 2012). "Thus, studies that combine clinical screening of obese patients and investigation of the functional defects of the obesity-linked MC4R variants can identify specific ways to correct these defects and are the first steps towards personalized medicine." (PMID 23251400, 2012). "In addition, some of the obesity-linked MC4R variants have defective binding affinities and/or signaling responses to endogenous or synthetic agonists." (PMID 23251400, 2012). "Common variants near MC4R are associated with fat mass, weight and risk of obesity." (PMID 22474595, 2012). "In the genetic determinism situation, if a subject is a carrier of the risk alleles of the FTO and the MC4R polymorphisms, such genetic susceptibility would irreversibly determine the obesity phenotype, and that genetic influence would be totally independent of lifestyle factors." (PMID 23284998, 2012). "Melanocortin 4 receptor, MC4R, mutations are the most common cause of monogenic severe obesity and missense variants within the gene have been associated with altered risk for common obesity." (PMID 22781276, 2012). "In addition, genetic POMC deficiency leads to obesity in humans and mice, and MC4-R deficiency leads to morbid obesity associated with enhanced adiposity and chronic hyperphagia." (PMID 22438946, 2012). "Therefore, further studies are necessary to identify the biological pathways through which the MC4R polymorphisms increase obesity susceptibility." (PMID 23049848, 2012). "Meta-analysis of association between MC4R polymorphism and obesity risk under an additive model." (PMID 23049848, 2012). "In humans, a defective MC4R is the most common cause of inherited severe obesity." (PMID 22479599, 2012). "The obesity predisposing SNP variant near MC4R was associated with increased feeling of hunger, increased snacking, decreased satiety, and increased total, fat and protein energy intake, the effects of the variant on food-related parameters being observed both in children and adults." (PMID 22043165, 2011). "Variants in or near LEP, POMC, MC4R, and IL-6 genes confer a significant risk to human obesity." (PMID 21390334, 2011). "Furthermore, a SNP located 188 kb downstream of the MC4R coding sequence has been associated with a modest increase in the risk for obesity." (PMID 22043165, 2011). "Here, we examine the genetic effects of FTO and MC4R variants on obesity-related phenotypes." (PMID 19822564, 2011).
Obesity (continued). "Interestingly, humans with mutations in POMC and MC4R and mice with targeted deletions in these genes have an obesity phenotype." (PMID 21283731, 2011). "The results therefore strongly suggest that FTO and MC4R might be the only two major-effect genes for obesity with common variants in populations of European ancestry." (PMID 21552555, 2011). "Heterozygous mutations in MC4R are the commonest known cause of monogenic obesity." (PMID 21860632, 2011). "As both, common distant SNPs and functionally relevant low frequency genetic variation within MC4R, are associated with obesity, the MC4R might be an example for ‘synthetic association’." (PMID 21085626, 2010). "In addition to these rare mutations, the minor alleles of two MC4R non-synonymous polymorphisms (Val103Ile, Ile251Leu) have convincingly been shown to be protective against obesity." (PMID 21085626, 2010). "As we identified a relatively common risk haplotype (frequency of [A; G] of Haplo 3 equals to 15.7% in the 787 parents) covering the MC4R coding region, we also analyzed if the associations of obesity to the distal 3′ common SNPs represent an example of synthetic association." (PMID 21085626, 2010). "As expected, pairwise LD measures between the two non-synonymous MC4R polymorphisms and the two SNPs of the obesity haplotype are larger for D′ (range 0.475–1), whereas the respective r2 values were low (range 0.001–0.007) due to the low allele frequencies of these polymorphisms." (PMID 21085626, 2010). "Association analysis for the relationship between validated SNPs in the explored candidate genes and quantitative metabolic/obesity related variables in PCOS with genetic effect sizes estimates derived for an additive genetic (MC4R rs2229616 dominant genetic model) for the minor allele." (PMID 20092643, 2010). "On the other hand, some of the related effect sizes of these variants seem to vary longitudinally as shown here for MC4R and previously stressed by others while other genetic loci might only be relevant for (paediatric) extreme obesity such as TNKS/MSRA." (PMID 20421936, 2010). "However, we cannot exclude that other functional variants outside of the coding region of the MC4R contribute to the GWAS obesity association signal." (PMID 21085626, 2010). "VGF ablation blocks obesity, hyperglycemia and hyperinsulinemia in MC4R-deficient mice, so this protein may function in these outflow pathways to regulate sympathetic nervous system activity and lipid storage." (PMID 19863797, 2009). "We hypothesized that we would detect rare loss-of-function genetic variants similar to the link between obesity and rare variants in the leptin, leptin receptor and MC4R genes." (PMID 20016785, 2009). "We tested the hypothesis that rare loss-of-function ATXN2 variants cause obesity analogous to rare mutations in the leptin, leptin receptor and MC4R genes." (PMID 20016785, 2009). "In humans, mutations that reduce the function of the MC4R result in severe obesity." (PMID 18377640, 2008). "In humans, MC4R mutations that lead to an impaired receptor function are associated with obesity; in contrast, the most frequent polymorphism (Val103Ile, rs2229616; heterozygote frequency approximately 2%) was shown to be negatively associated with obesity." (PMID 18377640, 2008). "Heterozygous mutations in MC4R also cause obesity and tall stature in humans." (PMID 17764572, 2007). "The most common monogenic forms of human obesity are MC4R mutations." (PMID 17764572, 2007). "Heterozygous point mutations in MC4R account for 1–6% of severe cases of human obesity." (PMID 17668051, 2007). "Investigating the molecular mechanisms by which loss-of-function mutations in MC4R cause obesity has led to a panel of functional anomalies: abnormal MC4R membrane expression, a defect in the agonist response, and a disruption in the intracellular transport of this protein." (PMID 17196040, 2006).
Obesity (continued). "Crucially, administration of setmelanotide restored CaMKK2/AMPK activity, reactivated MC4R neurons, and normalized appetite and feeding behavior during fasting-refeeding and the long-term treatment of obese rats (60% reduction in food intake), ultimately reversing obesity (23% weight loss)." (PMID 41601974, 2026). "Therefore, we speculated that the drug may also be used in clinically severely obese HO patients because it specifically activates MC4R neurons and it can effectively regulate the hyperphagia and obesity caused by hypothalamic injury." (PMID 41601974, 2026). "Additionally, a 2018 study found women with extreme obesity carrying the MC4R rs17782313 polymorphism tend to have higher BMIs before surgery, are less likely to achieve a non-obese BMI (<30 kg/m2), and typically maintain a BMI > 35 kg/m2, indicative of treatment failure." (PMID 40005017, 2025). "Although the MC4R:c.216C>G variant may contribute to the patient’s metabolic profile, further functional studies are required to confirm its pathogenicity and elucidate its role in obesity pathogenesis." (PMID 40428329, 2025). "In control individuals with obesity, the decrease in medium-chain and long-chain fatty acids from 60 min was followed by the accumulation of fatty acids and glycerol to form monoglycerols and diacylglycerols; the accumulation of monoglycerols and diacylglycerols was attenuated in MC4R deficiency." (PMID 41102563, 2025). "Although MC4R loss-of-function mutations are strongly associated with obesity, our data indicate that MC4R may exert region-specific or compensatory roles, as the maternal diet induced lasting central and peripheral disturbances despite the absence of overt obesity." (PMID 40956393, 2025). "For example, setmelanotide, a melanocortin-4 receptor agonist, has shown efficacy in patients with impaired leptin-melanocortin signaling—a defect that may occur in patients with non-syndromic obesity (e.g., POMC deficiency) as well as in those with additional features (e.g., Bardet-Biedl syndrome)." (PMID 40523925, 2025). "Thus, mice lacking Gq/11 at the paraventricular nucleus of the hypothalamus develop severe hyperphagic obesity and are unable to respond to MC4R agonists, while obese mice with a MC4R-F51L mutation associated with human obesity, have a specific defect in Gq/11 signaling." (PMID 39807633, 2025). "However, some obesity-associated MC4R variants signal normally via cAMP, which has raised the possibility that they perturb other uncharacterized signaling pathways linking MC4R to the regulation of food intake." (PMID 38567654, 2024). "Moreover, an MC4R variant associated with protection from human obesity and lower BMI (V103I), which has been shown to have increased ligand-induced β-arrestin recruitment, has also been shown to lead to increased stimulation of Gq/11α signaling in response to α- and β-MSH." (PMID 38175730, 2024). "Our findings further demonstrate that targeting of MC4R to neuronal primary cilia is essential for the control of long-term energy homeostasis and suggest that genetic disruption of MC4R ciliary localization may frequently underlie inherited forms of obesity." (PMID 36692018, 2023). "For instance, the MC4R rs17782313 variant has been demonstrated to be significantly associated with a higher prevalence of snacking as was shown in both French children with obesity (p = 0.01) and Swiss adults with obesity (p = 0.04), as well as in Finnish adolescents (p = 0.04)." (PMID 38002939, 2023). "Therefore, BDNF and sirtuin 1 may mediate the association between the MC4R rs17782313 polymorphism and obesity as well as hyperglycemia, which requires further investigation to confirm." (PMID 37621650, 2023). "Interestingly, another polymorphic site near the MC4R gene, rs12970134, was also found to be strongly associated with obesity risk, with 24 studies out of 25 studies reporting a significant impact of the rs12970134 polymorphism on obesity risk (data not shown)." (PMID 37621650, 2023).
Obesity (continued). "A study examining the interaction of MC4R rs17782313 with mental stress and energy intake and the risk of obesity found that interactions of mental stress and energy intake with the MC4R minor allele genotype may be associated with an increased risk of obesity in Korean adults." (PMID 37072742, 2023). "Consequently, administration of pharmaceutical agents that agonize MC4R cause weight loss by suppressing energy intake and stimulating energy expenditure, whereas genetic or pharmacological inhibition of MC4R results in hyperphagia and obesity." (PMID 37780616, 2023). "Moreover, it was shown that the interaction of mental stress interactions and energy intake with the MC4R minor allele genotype may increase the risk of obesity in Korean adults." (PMID 37072742, 2023). "In addition to the decreased gene transcription caused by mutations in key areas of the MC4R promoter, obesity in people may also occur." (PMID 35268815, 2022). "However in the present study, MC4R mutation carriers and controls showed similar weight loss, consistent with previous studies in patients with obesity and heterozygous MC4R mutations submitted to a controlled and intensive program of restricted dieting and daily physical activity for 6 weeks." (PMID 36553534, 2022). "Moreover, mutations causing a deficiency in the MC4R protein have been associated with obesity." (PMID 36532520, 2022). "Additionally, mutations in MC3R and MC4R are associated with obesity." (PMID 36358958, 2022). "Mask3, which aggregates variants in genes that reached exome-wide significance—only MC4R meets this P-value threshold (P < 2.8x10-6)—provided the best-performing PRSrare-burden score, explaining 0.08% of variation in obesity and 0.39% of variation in extreme obesity liability." (PMID 35592775, 2022). "This study aimed to assess the relationship of obesity-related biochemical and behavioral factors with rs17782313 variant in overweight and obese people and then assess the risk of obesity regarding interaction biochemical and behavioral factors with MC4R rs17782313 genotypes." (PMID 36123585, 2022). "Thus, these three different interventions may be useful for the short-term treatment of obesity in MC4R Ile269Asn mutation carriers." (PMID 36553534, 2022). "In addition to providing 2 mechanistically distinct mouse models for MC4R-linked obesity, the study presents the first in vivo demonstration to our knowledge of MC4R-specific PC action, paving the way for the development of a targeted therapy for severely obese patients harboring MC4R mutations." (PMID 33434184, 2021). "The apparent poorer response to a treatment program, which has proven effective in treating children with obesity in general, may indicate that children carrying damaging MC4R mutations need a more explorative and likely more intensive program when aiming to reduce BMI SDS." (PMID 32921795, 2021). "In addition, patients were only genetically screened for MC4R mutations, and some participants may thus have other forms of monogenic obesity." (PMID 32921795, 2021). "Moreover, gain-of-function MC4R variants are associated with protection from obesity." (PMID 33761344, 2021). "Therefore, the MC4R-related pathway is involved in obesity risk." (PMID 34836030, 2021). "They confirmed the established association of rs12970134 SNP near the melanocortin 4 receptor (MC4R) with WC and proposed the variant might affect mRNA expression of MC4R, one of the most prominent genes for monogenic obesity, in the hypothalamus and other parts of the central nervous system." (PMID 34072523, 2021). "Taken together, these data suggest that the primary cause of obesity in WT-hMC4R mice was a decrease in MC4R agonist tone reflecting species differences in MC4R receptor relative to endogenous melanocortins, thus providing a potentially new model of MC4R-linked obesity." (PMID 33434184, 2021).
Obesity (continued). "Efforts to reduce obesity and maintain a healthy weight in carriers of MC4R LoF mutations, through diet and physical activity will likely need to begin early in life and be targeted in nature, to have an optimal chance of reducing the risks of developing obesity later in life." (PMID 34045736, 2021). "The present study aimed at determining whether pharmacological chaperones (PCs) that restore folding and plasma membrane trafficking by stabilizing near native protein conformation may represent valid therapeutic avenues for the treatment of melanocortin type 4 receptor–linked (MC4R-linked) obesity." (PMID 33434184, 2021). "Thus, it should be considered to screen children with obesity for MC4R mutations prior to treatment initiation to determine whether they may benefit from the standard program or if a more explorative program should be offered." (PMID 32921795, 2021). "We aimed at investigating whether FGF21 affects metabolism inmale and female mice with the lethal yellow (Ay) mutation, which results in MC4R blockage and obesity development.Obese C57Bl-Ay male and female mice were administered subcutaneously for 10 days with vehicle or FGF21 (1 mg per1 kg)." (PMID 33659800, 2020). "We observed that, compared with carriers who had obesity, the 28 carriers of normal weight have other inherited genetic variants that overall predispose them to a lower body weight, which may offset the risk caused by the MC4R mutation they carry." (PMID 32692746, 2020). "Furthermore, we observed that despite the key role of MC4R in obesity, the effects of pathogenic MC4R mutations may be countered, at least in part, by a low polygenic risk potentially representing other innate mechanisms implicated in body weight regulation." (PMID 32692746, 2020). "Therefore, it is important to determine whether MC4R SNPs are associated with cancer risk, which may help illuminate the potential biological mechanism between obesity and cancer development." (PMID 32899047, 2020). "Defects in ERK1/2 signaling may also contribute to obesity pathogenesis in MC4R mutation carriers." (PMID 33076233, 2020). "All the studies discussed in this section highlighted that the partial or total loss of MC4R function, due to MC4R mutations, as well as the SNP rs17782313, are positively correlated with altered appetite and dysfunctional eating patterns, promoting obesity and elevated BMI." (PMID 33202557, 2020). "A risk allele and an AA genotype of rs2331841 (MC4R) could increase the risk of obesity." (PMID 31781208, 2019). "Therefore an early assessment and detection of any possible dependencies between the MC4R risk alleles and diet, and next the modifications of their dietary patterns based on these results, can be an efficient strategy to prevent obesity and its metabolic consequences." (PMID 30945034, 2019). "Notably, NEGR1 and MC4R are—found to be associated with obesity across multiple lines of evidence." (PMID 29795655, 2018). "In addition, the SNPs in MC4R play an important role in the susceptibility to obesity." (PMID 27926527, 2017). "Of note, in an unpublished study from another center in our city, frequency of MC4R mutations was reported to be 8.6% among 93 obese children and adolescents (mean age 7.3±3.7 years) who started to gain weight before 6 years of age and had a history of early-onset obesity in a first-degree relative." (PMID 28218067, 2017). "Therefore, MC4R is the most commonly known monogenic cause of human obesity." (PMID 28615046, 2017). "Thus, the MC4R polymorphism and stress may interactively change eating behavior leading to overweight and obesity." (PMID 27213003, 2016). "Interestingly, there was a positive interaction between MC4R variants and mental stress levels that were associated with the risk of obesity after adjusting for age, gender, residence area, daily energy intake, smoking status and physical activity (interaction P = 0.0384)." (PMID 27213003, 2016).